XCR1 (X-C motif chemokine receptor 1)
Diseases named in the same sentence as XCR1 in open-access papers (continued):
Sharing a sentence is not in itself a finding about the gene and the disease.
experimental autoimmune encephalomyelitis (4 papers, 2023 to 2025). An autoimmune demyelinating disease of the central nervous system that is produced experimentally in animals by the injection of homogenized brain or spinal cord in Freund's adjuvant. "Cody D. Moorman developed CAR-T cells and CAR-Tregs targeting X-C motif chemokine receptor 1 (XCR1) on the surface of conventional type 1 dendritic cells (DC1) to suppress experimental autoimmune encephalomyelitis (EAE)." (PMID 40881712, 2025). "We investigated the role of Regnase-1 in cDC1 and its impact on experimental autoimmune encephalomyelitis (EAE) on Regnase-1fl/+ Xcr1-Cre+ and control mice." (PMID 41562059, 2025). "XCR1 CAR-T cell-mediated depletion of DC1 modestly suppressed the onset of Th1-driven experimental autoimmune encephalomyelitis (EAE), an animal model of multiple sclerosis." (PMID 37965348, 2023). "X-C motif chemokine receptor 1-specific chimeric antigen receptor T cells (XCR1-CAR-T) and CAR-Tregs led to the depletion of DC1, modestly suppressing the onset of Th1-driven experimental autoimmune encephalomyelitis." (PMID 40260258, 2025).
lung cancer (4 papers, 2021 to 2025). A malignant neoplasm involving the lung. "XCR1 is overexpressed in non‐small cell lung cancer and is associated with its bone metastasis." (PMID 33377624, 2021). "We confirmed that i.v. injection of Cyt c (5 mg/mouse every other day) caused the selective depletion of cDC1 (including that of XCR1+ migratory cDC1) but no cDC2 cells in the blood, tumor, and tumor-draining lymph nodes from mice bearing MCA205 fibrosarcomas or TC-1 lung cancers." (PMID 37623817, 2023).
rheumatoid arthritis (4 papers, 2014 to 2025). A chronic, systemic autoimmune disorder characterized by inflammation in the synovial membranes and articular surfaces. "In patients with rheumatoid arthritis, XCL1 manifests itself in the synovium, while XCR1 is a characteristic feature of infiltrating mononuclear and synovial cells." (PMID 38887195, 2024). "In line with this view, XCL1 has been detected in synovial fluid, and XCR1 have been detected in the infiltrated mononuclear cells and synoviocytes within synovial tissues of rheumatoid arthritis patients." (PMID 32849609, 2020). "Xcr1 is the receptor for Xcl1 and Xcl2, which were not part of our microarray, but it is known that Xcrl also plays a role in rheumatoid arthritis and in the recruitment of cells to arthritic joints." (PMID 24967215, 2014).
allergic asthma (3 papers, 2022 to 2023). A asthma with a basis in a pathological type I hypersensitivity reaction. "Whereas the Xcr1+ Irf8+Batf3+ cDC1 showed similar frequencies in all experimental conditions, Xcr1-Irf8+Batf3+ cDC1 frequencies were elevated in the allergic asthma model compared to the allergen tolerance model and controls." (PMID 37251386, 2023). "In order to understand functional differences between Xcr1+Irf8+Batf3+ cDC1 and Xcr1- Irf8+Batf3+ cDC1 clusters, we assessed differential gene expression in allergen-naïve control mice that had not been referred to the allergic asthma model or allergen tolerance model." (PMID 37251386, 2023).
injury (3 papers, 2020 to 2024). Damage inflicted on the body as the direct or indirect result of an external force, with or without disruption of structural continuity. "Based on the available literature and our results, we suggest that XCL1 deserves further study, especially because XCR1 and ITGA9 seem to be important novel targets with beneficial properties for pharmacological intervention after brain injury." (PMID 33185818, 2020). "Moreover, both XCL1 receptors (XCR1 and ITGA9), seem to be important novel targets with beneficial properties for pharmacological intervention after nerve injury." (PMID 36618360, 2022).
asthma (2 papers, 2023). "In addition, we recently reported that iNKT cells contribute to the development of asthma by secreting X-C motif chemokine ligand-1, which recruits conventional X-C motif chemokine receptor 1-expressing type-1 dendritic cells into the lungs: this then stimulates the Th2 responses that drive asthma." (PMID 37917548, 2023).
Autoimmunity (2 papers, 2023 to 2025). The occurrence of an immune reaction against the organism's own cells or tissues. "Mice were periodically weighed and monitored to determine if engraftment of self-reactive CD3+ XCR1 CAR-T cells resulted in overt autoimmunity." (PMID 37965348, 2023). "Thus, CNS-specific MOG CAR-Tregs exhibited enhanced protection against CNS-directed autoimmunity compared with DC1-specific XCR1 CAR-Tregs." (PMID 37965348, 2023). "Together, these results suggest that XCR1 CAR-T cells engraft in immunodeficient RAG2−/− mice and eliminate DC1 in lymphoid organs without acute autoimmunity." (PMID 37965348, 2023). "The XCR1 CAR was functional and engendered T cells with cytotoxic capabilities that led to systemic depletion of XCR1+ DC1 in vivo without any sign of overt autoimmunity due to the self-reactive CAR receptor." (PMID 37965348, 2023).
cutaneous melanoma (2 papers, 2023 to 2025). A primary melanoma arising from atypical melanocytes in the skin. "For example, the cutaneous melanoma antigens were cross-presented preferentially by migratory CD103+XCR1+ and CD103-XCR1+ skin-derived DC, and migratory cDC1 dominantly cross-presented herpes simplex virus and skin-derived self-antigens." (PMID 40491915, 2025).
medulloblastoma (2 papers, 2013 to 2015). A malignant, invasive embryonal neoplasm arising from the cerebellum. "When hAT-MSCs were co-cultured with medulloblastoma-BTICs, the expression levels of CCR4, CCR5, CCR7, XCR1, CXCR1, CXCR4, PDGFR-bb, KDR and TEK were increased, while the levels of CX3CR1, IL1R, IL6R, IL8R, IGF1R and CD44 were decreased (p<0.05)." (PMID 26076490, 2015).
multiple sclerosis (2 papers, 2023 to 2025). A progressive autoimmune disorder affecting the central nervous system resulting in demyelination. "In a preclinical study on the treatment of multiple sclerosis, the transfer of X-C motif chemokine receptor 1 (XCR1)-specific CAR Treg cells into EAE, an animal model of multiple sclerosis, successfully inhibited T helper 1 cells (Th1)-driven EAE." (PMID 40873568, 2025).
type 1 diabetes (2 papers, 2018 to 2025). "The only previous study to report XCR1 expression in the CNS describes increased levels in a mouse model of type 1 diabetes (streptozotocin model)." (PMID 29588250, 2018).
acquired immunodeficiency (1 paper, 2014). "Both cross-presenting XCR1+ DC and virus immune evasion genes play a key role in setting a balance between CMV and their hosts that may benefit both parties in the absence of developmental, genetic or acquired immunodeficiency of the host." (PMID 25120535, 2014).
Allergy (1 paper, 2023). An allergy is an immune response or reaction to substances that are usually not harmful. "We identified the well-known Xcr1+Irf8+Barf3+ cDC1 cluster as well as an Xcr1-Irf8+Batf+ cDC1 cluster which was present in allergen-naïve control mice and which expanded at least in frequencies during type-2 inflammation induced in a murine allergy model." (PMID 37251386, 2023).
atherosclerosis (1 paper, 2025). A disease characterized by the build-up of fatty material and calcium deposition in the arterial wall resulting in partial or complete occlusion of the arterial lumen. "To elucidate the causal relationship between Xcl1 and Xcr1+ cDC1 in the development of atherosclerosis, and more importantly, to experimentally verify Xcl1 as a potential therapeutic target for atherosclerosis treatment, we established the Xcl1 and Apoe double knockout mice." (PMID 40934103, 2025). "Most importantly, we have successfully demonstrated that targeting the chemokine Xcl1, the ligand of Xcr1, can effectively inhibit atherosclerosis." (PMID 40934103, 2025). "Since we elucidated the critical role of Xcr1+ cDC1 cells in atherosclerosis, our aim was to test the therapeutic potential of inhibiting this specific cell type during disease progression." (PMID 40934103, 2025). "Our work paves the way to discover novel solutions for the treatment of atherosclerosis by targeting Xcl1 and Xcr1+ cDC1 cells." (PMID 40934103, 2025). "To further elucidate the dynamics of Xcr1+ cDC1 cells within the plaque during the progression of atherosclerosis, we carried out immunohistochemical analyses of these cells in the lesioned aortic root." (PMID 40934103, 2025). "In summary, our findings identify Xcl1 as a potential therapeutic target for atherosclerosis therapy, though its cellular origins and regulation of lesional Xcr1+ cDC1 and T cells dynamics require further studies." (PMID 40934103, 2025). "Subsequently, by further crossing, we obtained Xcr1Cre-Gfp Rosa26LSL-DTA Apoe–/– mice to create a complex genetic model, in which Xcr1+ cDC1 is depleted in vivo in the context of atherosclerosis." (PMID 40934103, 2025). "Collectively, these data suggest that Xcl1 promotes atherosclerosis by recruiting Xcr1+ cDC1 cells, and facilitating CD8+ T cell accumulation in lesions." (PMID 40934103, 2025). "By delineating the specific contributions of Xcr1+ cDC1, we may identify novel therapeutic targets and develop more targeted and effective strategies for the prevention and treatment of atherosclerosis." (PMID 40934103, 2025). "As Xcr1 is the sole receptor for Xcl1, and Xcl1 selectively attracts Xcr1+ cDC1 cells in both mice and humans, we performed Xcl1 knockout on the background of Apoe–/– mice and assessed the impact on atherosclerosis development." (PMID 40934103, 2025). "Coupled with the data we obtained from murine and human samples, where Xcr1+ cDC1 cells exist in the aortic plaque and their accumulation is correlated with disease progression, we conclude that Xcr1+ cDC1 is essential for the development of atherosclerosis." (PMID 40934103, 2025). "Nevertheless, the precise role of Xcr1+ cDC1 cells in atherosclerosis remains undetermined." (PMID 40934103, 2025). "Very interestingly, in the Xcr1+ cDC1-depleted mice, atherosclerosis was significantly ameliorated." (PMID 40934103, 2025). "Therefore, our study, which employed genetic models to deplete Xcr1+ cDC1 in vivo in hyperlipidemic mice, has unequivocally determined the essential role of this specific cell type in the development of atherosclerosis." (PMID 40934103, 2025). "Therefore, an investigation to understand the roles of Xcr1+ cDC1 in the context of atherosclerosis and to identify therapeutic targets is highly warranted." (PMID 40934103, 2025). "Therefore, our experiments provided data indicating the enrichment of Xcr1+ cDC1 cells in aortic lesions in both humans and mice, and demonstrated that the accumulation of Xcr1+ cDC1 cells was significantly greater during the progression of atherosclerosis." (PMID 40934103, 2025). "To understand the role of Xcr1+ cDC1 in regulating the development of atherosclerosis, we established the Xcr1Cre-Gfp Apoe–/– mice in which the Cre recombinase and eGFP was co-expressed under the control of the endogenous Xcr1 promoter following the start codon." (PMID 40934103, 2025).
atherosclerosis (continued). "Attenuated T cell activation might account for the mitigated atherosclerosis in Xcr1+ cDC1-depleted mice." (PMID 40934103, 2025). "Our data showing Xcr1+ cDC1-dependent CD4 and CD8 T cell activation in atherosclerotic plaques is in line with the new paradigm for cDC1s as a platform for both CD4 and CD8 T cell responses in the novel context of atherosclerosis." (PMID 40934103, 2025).
Cerebral ischemia (1 paper, 2013). Restriction of arterial blood supply to the brain associated with insufficient oxygenation to support the metabolic requirements of the tissue. "Only chemokine ligand-9 (CXCL9), chemokine ligand-11 (CXCL11), and chemokine receptor-1 (XCR1) have not been, to our knowledge, previously examined with their relations to cerebral ischemia." (PMID 24244400, 2013).
cholangiocarcinoma (1 paper, 2023). A carcinoma that arises from the intrahepatic biliary tree (intrahepatic cholangiocarcinoma) or from the junction, or adjacent to the junction, of the right and left hepatic ducts (hilar cholangiocarcinoma). "We also found strong positive correlations between XCR1 and CXCR3 in a variety of tumors, including SKCM, UVM (uveal melanoma), SARC, MESO (mesothelioma), PCPG, BRCA, CHOL (cholangiocarcinoma), and OV." (PMID 37895310, 2023).
colorectal tumor (1 paper, 2023). "First, we created a 7-plex immunofluorescent staining panel to be used on a colorectal tumor tissue (CRC1) consisting of a tumor marker (EPCAM), T-cell markers (CD3, CD4, and CD8), and myeloid markers (CD163, HLA-DR, and XCR1)." (PMID 37731497, 2023).
diffuse large B-cell lymphoma (1 paper, 2023). "Furthermore, the genetic alteration analysis of the alteration frequency with XCR1 was >4%, and the primary types were deletion and missense, such as in DLBC (Lymphoid Neoplasm Diffuse Large B-cell Lymphoma), KIRC, and SKCM, etc.." (PMID 37895310, 2023).
Hepatic steatosis (1 paper, 2023). Steatosis is a term used to denote lipid accumulation within hepatocytes. "Moreover, XCR1+ cDC1s, efficient at cross-presenting antigens to CD8+ T cells, were reported to increase hepatic steatosis and contribute to liver pathology, which was associated with inflammatory T cell reprogramming in the liver-draining lymph nodes." (PMID 37140993, 2023).
hepatitis C (1 paper, 2025). "Single-cell RNA-seq analysis confirmed the impact of type I IFN on fibrosis progression, showing reduced expression of viral protein interaction genes (Ccl12, Xcr1) and hepatitis C-related genes (IFNg, Ifit1) in the Type I IFN blockade group." (PMID 40260261, 2025).
Huntington disease (1 paper, 2021). Huntington disease (HD) is a rare neurodegenerative disorder of the central nervous system characterized by unwanted choreatic movements, behavioral and psychiatric disturbances and dementia. "Among the XCR1 high expression subgroup, only butanoate metabolism, cardiac muscle contraction, Huntington's disease, oxidative phosphorylation, and Parkinson's disease pathways were enriched, among which there is no classical tumor‐associated signaling pathway." (PMID 33377624, 2021).
kidney cancer (1 paper, 2023). Primary or metastatic malignant neoplasm involving the kidney. "The efficiency of the knockdown of the XCR1 genes was confirmed by RT-qPCR results shown, in which the mRNA expression level of the XCR1 genes was reduced after transfection of specific siRNA into kidney cancer 786-O and CAKI-1 cells." (PMID 37816979, 2023). "siRNAs were transfected into kidney cancer 786-O and CAKI-1 cell lines to explore the detailed role of XCR1 genes in oncogenicity." (PMID 37816979, 2023). "Meanwhile, a lack of XCR1 genes inhibited EMT in kidney cancer, as evidenced by decreased protein levels of N-calmodulin and Vimentin and increased E-calmodulin." (PMID 37816979, 2023). "Also, the lack of the XCR1 genes inhibited EMT in kidney cancer, as evidenced by decreased protein levels of N-calmodulin and Vimentin and increased E-calmodulin." (PMID 37816979, 2023).
lymphoma (1 paper, 2022). A malignant (clonal) proliferation of B- lymphocytes or T- lymphocytes which involves the lymph nodes, bone marrow and/or extranodal sites. "The chemokine receptor expression profiles of de novo DLBCL and tFL substantially differed from those of GC-B, with at least 5-fold higher expression of 15 out of the 18 investigated chemokine receptors (CCR1–CCR9, CXCR1, CXCR2, CXCR6, CXCR7, CX3CR1 and XCR1) in these lymphoma subtypes." (PMID 35887224, 2022).
MALT lymphoma (1 paper, 2015). An indolent, extranodal type of non-Hodgkin lymphoma composed of small B-lymphocytes (centrocyte-like cells). "In comparing gastric to extragastric MALT lymphomas, the upregulation of CXCR1 and CXCR2 accompanied by downregulation of CCR8 and CX3CR1 and loss of XCR1 expression in extragastric MALT lymphomas appear to be key determinants for the site of origin of MALT lymphomagenesis." (PMID 25922601, 2015).
myeloma (1 paper, 2024). "A myeloma mouse model was performed by intravenous transplantation of Vk*MYC myeloma cells into XCR1-Diphtheria toxin receptor (DTR) knock-in or wild-type mice." (PMID 39474418, 2024). "Interestingly, mature CD11c+CD8a+XCR1+CD11b- cDC1s accumulated in the bone marrow 14 and 24 days after myeloma transplantation." (PMID 39474418, 2024). "To test whether cDC1 supports or inhibits the progression of myeloma, we used a Vk*MYC myeloma mouse model that can be used to monitor the tumor based on CD155 and IgG2b expression, and the XCR1-DTR mouse line that can inductively deplete cDC1 in the body." (PMID 39474418, 2024).
neuropathy (1 paper, 2022). A disorder affecting the nervous system that manifests with pain, tingling, numbness, and/or muscle weakness. "It remains unknown how XCR1 and ITGA9 are involved in nociceptive transmission; however, their role seems to be extremely important in neuropathy, as our previous research proved the strong pronociceptive properties of their ligand, XCL1, in naive animals." (PMID 36618360, 2022).
osteoporosis (1 paper, 2025). A condition of reduced bone mass, with decreased cortical thickness and a decrease in the number and size of the trabeculae of cancellous bone (but normal chemical composition), resulting in increased fracture incidence. "Bone‐targeting AAV of Xcr1 can improve bone formation in osteoporosis mice, suggesting that XCR1 can be a new susceptibility gene for osteoporosis." (PMID 39704037, 2025). "Cis‐eQTL analysis showed that the osteoporosis‐susceptibility SNP rs4683184‐A allele was significantly associated with increased expression of XCR1 (P = 5.59 × 10−9)." (PMID 39704037, 2025). "Together, our results demonstrate that bone targeting overexpression of Xcr1 could protect against bone loss in the OVX mice model, and Xcr1 could be an effective target for osteoporosis treatment in vivo." (PMID 39704037, 2025). "Bone‐targeting AAV of XCR1 improves bone formation and increases bone mineral density in mice with osteoporosis." (PMID 39704037, 2025). "We used bone‐targeting AAV of Xcr1 (AAV‐DSS‐Xcr1) to treat osteoporosis mice and found that Xcr1 improved bone formation in osteoporosis mice." (PMID 39704037, 2025). "Bone‐targeting adeno‐associated virus (AAV) carrying the Xcr1 gene could improve bone formation and increase BMD in osteoporosis mice." (PMID 39704037, 2025). "Bone‐targeting AAV of Xcr1 could improve bone formation and increase BMD in mice with osteoporosis, suggesting that XCR1 could be a new susceptibility gene for osteoporosis." (PMID 39704037, 2025). "In summary, our study reveals that RUNX2 phase separation mediates the long‐range interaction between non‐coding susceptibility SNP rs4683184 and target gene XCR1, and then regulates the expression of XCR1 involved in osteoblast differentiation and osteoporosis." (PMID 39704037, 2025). "To evaluate the role of Xcr1 in osteoporosis in vivo, we performed ovariectomy (OVX) surgery in 3 months old female wild‐type (WT) mice, and utilized bone targeting AAV to overexpress Xcr1 (AAV‐DSS‐Xcr1) by intra‐articular injection." (PMID 39704037, 2025). "However, the precise function of XCR1 in osteoporosis and osteoblasts remained unknown." (PMID 39704037, 2025). "Further, we found that targeted overexpression of Xcr1 in bone improved cortical bone BMD, trabecular bone BMD, Tb.N, BV/TV, and BS/TV, while reducing Tb.Sp (trabecular separation) in mice with osteoporosis." (PMID 39704037, 2025).